SFTPA1 (surfactant protein A1)
Diseases named in the same sentence as SFTPA1 in open-access papers (continued):
Sharing a sentence is not in itself a finding about the gene and the disease.
retinal degeneration (1 paper, 2018). Degeneration of the retina. "We hypothesized that gene deletion of Sftpa1 and Sftpd (Sftpa1tm1Kor/J and Sftpd-/-) results in early retinal degeneration in these mice." (PMID 29969487, 2018). "We hypothesized that deletion of Sftpa1 and Sftpd results in early retinal degeneration." (PMID 29969487, 2018). "We can therefore conclude that loss of Sftpa1 and Sftpd do not result in retinal degeneration." (PMID 29969487, 2018).
viral infections (1 paper, 2015). "The MX, TRIM22, ISG15, OAS, and SFTPA1, B gene are important effectors of innate immune response against viral infections." (PMID 25883591, 2015).
tumor (11 papers, 2017 to 2024). "The single-cell RNA-Seq data also demonstrate robust expression of AT2 cell–specific Sftpc (encoding SPC) and Sftpa1 (encoding surfactant protein A) genes in cells labeled as tumor cells." (PMID 35763345, 2022). "The second notable observation was that only one protein—SFTPA1—was predominantly expressed by lung tumor tissue compared to other tumor tissues, whereas most proteins were expressed in a wide range of cancer types." (PMID 37264016, 2023). "To further explore the relationship between SFTPA1 and tumor immune cell infiltration landscape, we utilized the CIBERSORT algorithm to first calculate the relative proportion of 22 types of immune cells in the TCGA LUAD." (PMID 34181042, 2022). "Our results showed that SFTPA1 was down-regulated in the tumor tissues compared with the normal tissues in LUAD." (PMID 34181042, 2022). "In our study, has-miR-590-3p is highly expressed in the tumor tissues and is inter‐regulated with lncRNAs to promote tumor development by targeting SFTPA1, which requires further research for verification." (PMID 34181042, 2022). "The deletion of SFTPA1 (alias, SPA) gene in NSCLCs is associated with tumor progression." (PMID 33224886, 2020). "Notable genes displaying similar expression patterns in AFCs and tumour cells compared with FCs included TFF3 and TG (signature genes of FCs), IGHG4 and SFRP2 (signature genes of FCs) and FN1 and SFTPA1 (signature genes of tumour cells)." (PMID 38426403, 2024). "The findings of our study describe the SFTPA1 expression profile in multiple databases and was validated in BALB/c mice, human tumor tissues, and paired normal tissues using an immunohistochemistry assay." (PMID 34181042, 2022). "SFTPA1, FOXL1, and MAPK11 are tumor-characteristic molecular markers." (PMID 38495669, 2024).
cancer (10 papers, 2015 to 2024). A tumor composed of atypical neoplastic, often pleomorphic cells that invade other tissues. "Similar to the overall transcriptional profile of cancer cells in the GG component samples, surfactant-associated proteins (SFTPA1, SFTPA2, SFTPB, SFTPC, and SFTPD) were highly expressed, and the expression level was higher than that of other cancer cell subclusters of the GG component samples." (PMID 35874770, 2022). "Most cancer cells in the GG components expressed SFTPA1 and SFTPA2, although cancer cells in the S components of different individuals had diverse distribution patterns." (PMID 35874770, 2022). "Targeted sequencing was performed using a surgical specimen and it showed that the cancer harbored noncoding indels in the SFTPA1 and SFTPB genes." (PMID 30999697, 2019). "A cancer panel was designed in-house based on data published previously to analyze the noncoding regions of six genes—surfactant protein A1, B, and C, as well as albumin, lipase, and thyroglobulin." (PMID 30999697, 2019). "Furthermore, cancer cells in GGN highly expressed alveolar type II (AT2) cell-related marker genes (SFTPA1, SFTPA2, SFTPB, ABCaC3), suggesting that cancer cells in GGN might originate from AT2 cells." (PMID 37745301, 2023). "First, we used the SingleR package and the known markers of cancer and alveolar cells to identify a cancer cluster and alveolar cluster; EPCAM and SOX4 were used to mark the cancer cluster; SFTPC and SFTPA1 to mark the alveolar cluster; CAPS and TPPP3 to mark epithelial cells." (PMID 33783985, 2021).
infection (6 papers, 2013 to 2025). The state of being infected such as from the introduction of a foreign agent such as serum, vaccine, antigenic substance or organism. "Infection led to downregulation of surfactant genes (SFTPA1, SFTPC, SFTPD), cellular transition from functional ATIIs to proliferative ATIIs (mitotic), and PATS-like states, mimicking injury-induced alveolar regeneration pathways overserved in vivo." (PMID 41502560, 2025). "Reduced expression of SFTPA1 was also observed in infection studies with chickens using ILTV (Infectious Lanryngotracheitis Virus) and Avian Influenza Virus H9N2, possibly mediated by virus induced IFN." (PMID 28351377, 2017). "Sftpa1, Sftpb, Sftpc, and Abca3 also declined to 50–75% below uninfected control while Sftpd levels were stable for the first 7 days after infection in the lungs of B2−/− mice." (PMID 28779131, 2017).
adenocarcinoma (3 papers, 2021 to 2023). A common cancer characterized by the presence of malignant glandular cells. "The major clinical implication so far described in SRG mutations relates to the high frequency (37%) of lung carcinoma (mostly of the adenocarcinoma type) alone (12%) or in combination with pulmonary fibrosis (25%) in SFTPA1/SFTPA2 adult carriers." (PMID 36552935, 2022).
infectious disease (2 papers, 2011 to 2018). A disorder directly resulting from the presence and activity of a microbial, viral, or parasitic agent in humans. "CGN1 is the first gene in the bovine collectin locus, a 260-kb region on chromosome 28 which includes the CL46, CL43, SFTPD, MBL1, and SFTPA1 genes, and several of these genes have been implicated in infectious disease susceptibility." (PMID 29744529, 2018). "Only a few studies have addressed the role of the genetic variability at SFTPA1, and SFTPA2 in infectious diseases." (PMID 21310059, 2011).
respiratory disease (1 paper, 2021). "One of the siblings also had heterozygous SFTPA1:c.675C > G, p.Asn225Lys, which resulted in a more severe respiratory disease." (PMID 33526882, 2021). "The results here show significant respiratory diseases associated with likely pathologic variants, such as ABCA3:p.Val1399Met, MUC5B:p.Ile4979Thr, MUC5B:p.Gly5580Arg, MUC5B:p.Glu5621*, SCNN1B:p.Arg206Trp, SCNN1B:p.Glu468Lys, and SFTPA1:p.Gly98Ala." (PMID 33526882, 2021).
SFTPA1 also shares sentences with these, for which no sentence is quoted: cystic fibrosis (3 papers); otitis media (2); respiratory infection (2); RSV bronchiolitis (2); bacteremia (1); breast carcinoma (1); central nervous system cancer (1); co-infection (1); colon cancer (1); colorectal cancer (1); coronary heart disease (1); diabetes mellitus (1); diarrheal disease (1); ischemic stroke (1); kidney disease (1); lung squamous cell carcinoma (1); pneumococcal bacteremia (1); pneumonia (1); prostate carcinoma (1); squamous cell carcinoma (1); vascular Ehlers-Danlos syndrome (1).